SNORD18B (small nucleolar RNA, C/D box 18B)
Synonyms: U18B
Gene: Small nucleolar RNA gene on chromosome 15 (66,502,020 to 66,502,091, reverse strand). Ensembl gene ENSG00000202529.
Gene Ontology:
Biological process: RNA processing
Cellular component: nucleolus
Homologues: Orthologues: chimpanzee SNORD18 (100% identical), macaque SNORD18 (100% identical), dog SNORD18 (96% identical), pig SNORD18 (93% identical), tropical clawed frog SNORD18 (78% identical). Paralogues in human: SNORD18C (85% identical), SNORD18 (83% identical), SNORD18 (79% identical), SNORD18A (75% identical).